U3 (Small nucleolar RNA U3 )
Synonyms: LOC124901859
Gene: Small nucleolar RNA gene on chromosome 7 (148,389,645 to 148,389,859, forward strand). Ensembl gene ENSG00000199370.
Gene Ontology:
Biological process: RNA processing
Cellular component: nucleolus
Homologues: Orthologues: chimpanzee U3 (96% identical), macaque U3 (92% identical). Paralogues in human: SNORD3P1 (80% identical), U3 (78% identical), SNORD3E (76% identical), U3 (76% identical), U3 (75% identical), SNORD3H (75% identical), SNORD3D (73% identical), SNORD3G (73% identical), U3 (73% identical), U3 (72% identical), U3 (71% identical), U3 (70% identical), and 13 more.